TRPV4 (transient receptor potential cation channel subfamily V member 4)
Diseases named in the same sentence as TRPV4 in open-access papers (continued):
Sharing a sentence is not in itself a finding about the gene and the disease.
tumor (96 papers, 2013 to 2025). "In our research, TRPV4 was positively associated with neutrophils, so it was possible that TRPV4 regulated tumor progression by affecting the function of neutrophils." (PMID 35813831, 2022). "We previously showed that tumor cell conditioned media (TCM) causes abnormal tube formation in vitro (via downregulation of TRPV4), and that the exosome inhibitor, GW4869, attenuates this effect." (PMID 35004649, 2021). "In particular, TRPV4-mediated Ca2+ signals are implicated in tumor-derived endothelial cells (TECs) migration via a membrane-stretch activated arachidonic acid release and subsequent actin remodeling and TRPV4 insertion in the plasma membrane." (PMID 33132914, 2020). "Arachidonic acid (AA)-based calcium entry has been linked to angiogenesis in breast-derived tumor endothelial cells (TECs), and TRPV4 is upregulated in breast TECs compared to healthy endothelial cells." (PMID 32843668, 2020). "Our IHC analysis in the clinical samples demonstrated the association of relatively high TRPV4 expression with metastatic lesions, high grade tumor, as well as poorer OS and DFS." (PMID 28530703, 2017). "Recent reports have linked PAR-2 and TRPV4 activation, where TRPV4 is known to enhance EC proliferation and arachidonic acid-mediated tumor EC migration." (PMID 26573921, 2015). "The acid-sensing ion channels ASIC1 and ASIC2, as well as the transient receptor potential vanilloid channels TRPV1 and TRPV4, are proton-gated cation channels that can be activated by low extracellular pH (pHe), which is a hallmark of the tumor microenvironment in solid tumors." (PMID 34199609, 2021). "Moreover, the reduced expression of TRPV4 in tumor endothelial cells caused an increase in proliferation, confirming that these receptors may regulate abnormal tumor angiogenesis." (PMID 38730655, 2024). "In an orthotopic PDAC model, TRPV4-KO mice exhibited a significant reduction in tumor size, circulating inflammatory cytokines, tissue inhibitor of metalloproteinases-1 (TIMP1), and premetastatic niche markers, serum amyloid A (SAA) proteins." (PMID 41100488, 2025). "LCL/ZnO regulated the homeostasis of tumor vascular endothelial cells by activating TRPV4-eNOS signalling." (PMID 40235732, 2025). "Evidence suggests that TRPV1, TRPV2, and TRPV4 are overexpressed in several tumor types, contributing to processes such as tumor survival, proliferation, metastasis (migration and invasion), and angiogenesis." (PMID 40006844, 2025). "Over the past decades’ studies have established connections between TRPV4 and a diverse spectrum of conditions, including inflammation, peripheral neuropathy, skeletal dysplasia, vascular tone regulation, and tumor progression, among others." (PMID 39333347, 2025). "The co-regulation of TRPC1 and TRPV4 plays a crucial role in tumor angiogenesis, involving Caveolin-1 and IP3R3." (PMID 40078961, 2025). "TRPV4 is downregulated in tumor endothelial cells due to exosomal signals derived from malignant cells, leading to disrupted vascular architecture and abnormal angiogenesis." (PMID 40813985, 2025). "Previous studies have shown that tumor stiffness activates TRPV4 and induces Ca2+ influx, which can further alter matrix stiffness by modulating the cytoskeleton and enzyme activities." (PMID 39895789, 2025). "For example, recent findings show that TRPV4 plays a key role in tumor cell dissemination from three-dimensional tumor spheroids." (PMID 39333347, 2025). "The singlet oxygen (1O2) generated by LCL/ZnO activates signaling pathways in tumor-derived endothelial cells, including transient receptor potential vanilloid-4 (TRPV4) and endothelial nitric oxide synthase (eNOS), which contribute to vascular normalization." (PMID 40235732, 2025). "The increased expression of ERK1/2 is suggestive of tumor progression, and its co-expression with TRPV4 on the same DRG neuronal cells was also confirmed, inferring the mutual synergistic roles of these proteins in pain transduction." (PMID 38730655, 2024).
tumor (continued). "The activation of TRPV4 has been shown to normalize the tumor vasculature and improved the efficacy of anticancer therapy." (PMID 38667297, 2024). "For example, the activation of TRPV1 and TRPV4 in lung cancer cells induces Ca2+ influx, and eventually leads to tumor cell proliferation, migration and apoptosis by stimulating the MAPK pathway to promote cell apoptosis and increase ROS production." (PMID 38505262, 2024). "Co-administering a TRPV4 activator, such as cannabidiol, with cisplatin can improve the targeted distribution of cytotoxic drugs to the tumor site and effectively inhibit tumor development." (PMID 39337406, 2024). "For example, TRPV4, a mechanosensitive ion channel, decreases malignant progression by selectively inhibiting tumor endothelial cell proliferation to reduce tumor angiogenesis." (PMID 38734935, 2024). "Another study showed that TRPV4 expression downregulates angiogenesis and that TRPV4 expression is downregulated and Ca2+ influx is reduced in tumor endothelial cells compared to healthy endothelial cells." (PMID 38505262, 2024). "All the evidence suggests that the functionality of TRPV4 in tumor cells is truly complex and it needs to be further studied." (PMID 36837670, 2023). "Xie and colleagues showed that calcium-sensitive receptor (CasR) activation triggered TRPV4-mediated Ca2+ entry, followed by Akt and β-catenin phosphorylation and tumor progression." (PMID 37762011, 2023). "TRPV4 expression is higher in breast metastatic lesions compared to normal breast tissue and invasive ductal carcinomas, and its expression increases with tumor grade and size." (PMID 37892239, 2023). "This research demonstrates a novel mechanism by which GL-V9 inhibits tumor metastasis by reducing TRPV4-regulated sc polarity, and provides a promising candidate for HCC therapy." (PMID 37369706, 2023). "Increased lymph node metastasis, deeper tumor invasion, a higher TNM stage, poor overall survival and poor disease-free survival have been linked to TRPV4 overexpression." (PMID 37762011, 2023). "The mechano-response of TRPV4 has been utilized to inhibit the abnormal angiogenesis formed by tumor endothelial cells (TECs)." (PMID 37864030, 2023). "Overexpression of mechanosensitive ion channel TRPV4 restores the mechanosensitivity to substrate rigidity of tumor endothelial cells (TECs) and reduces their migration." (PMID 37864030, 2023). "Studies in the Lewis lung carcinoma tumor model of TRPV4 (ECKO) mice demonstrated that endothelial TRPV4 is a critical modulator of vascular integrity and tumor angiogenesis and deletion of TRPV4 promoted tumor angiogenesis, growth, and infiltration." (PMID 36768856, 2023). "According to recent studies, tumor growth and metastasis are significantly increased in a syngeneic Lewis lung carcinoma tumor model of endothelial-specific TRPV4 knockout (TRPV4-ECKO) mice compared to wild-type mice." (PMID 37892239, 2023). "In this study, we showed that TET1 and TRPV4 expression was increased in L4–6 DRG after inoculation with Walker 256 tumor cells in rat tibia." (PMID 37190609, 2023). "The suppression of TRPV4 expression in keratinocytes has been correlated with the increase in cytokines and prostaglandins within the tumor milieu." (PMID 37892239, 2023). "Like other channels, the modulation of TRPV4 channel expression is observed to be closely related to tumor formation progression and metastasis." (PMID 37892239, 2023). "Transient receptor potential vanilloid type 4 (TRPV4) can function as an oncogene or tumor suppressor depending on the tumor types." (PMID 36619170, 2022). "Activation of TRPV4 normalized tumor vasculature and improved cisplatin therapy from a transgenic adenocarcinoma mouse prostate model." (PMID 36619170, 2022). "TRPV4 downregulation in murine endothelial cells also destabilizes tumor vessel integrity due to abnormal stiffness sensing and reduced VE-cadherin expression at cell-cell contacts." (PMID 36158191, 2022).
tumor (continued). "The higher levels of tumor-infiltrating macrophages, myeloid dendritic cells, neutrophils, and CD4+ T cells with high TRPV4 expression were significantly associated with shorter survival." (PMID 35813831, 2022). "The low in situ expression of Ki-67 in the TRPV4-knockdown tumor tissues also confirmed its suppressive effect on NPC cell growth." (PMID 36619170, 2022). "Subsequently, A375 was selected for subcutaneous in situ tumor modeling for its highest expression of TRPV4, and the intratumoral expression of TRPV4 was obviously higher than in normal skin tissues." (PMID 36499486, 2022). "The finding is supported by an earlier study, in which high pericytes-stabilized vessels were seen on tumor vessels following activation of TRPV4." (PMID 36143906, 2022). "TRPV4 inhibition reduces tumor growth, decreases invasion into the surrounding brain tissue, and significantly prolongs the survival time of mice." (PMID 36158191, 2022). "TRPV4 expression was markedly decreased in tumor tissues from the TRPV4-knockdown group compared to the control group." (PMID 36619170, 2022). "In the context of prostate cancer, TRPV4 expression in murine tumor endothelial cells regulates Ca2+ influx and Rho activity in response to substrate stiffness." (PMID 36158191, 2022). "We have recently demonstrated that conditioned media from human lung tumor cells (A549) downregulate TRPV4 channels and transform normal endothelial cells to a tumor endothelial cell-like phenotype and induce abnormal angiogenesis in vitro, via t-EVs." (PMID 35004649, 2021). "We have previously shown that the expression of mechanosensitive ion channel, TRPV4, is downregulated in tumor endothelial cells and activation of TRPV4 normalizes the tumor vasculature and improves chemotherapy." (PMID 35004649, 2021). "We first assessed TRPV4 expression using tumor tissue data from TCGA and normal tissue data from TCGA and the GTEx database." (PMID 34262942, 2021). "On the other hand, in tumor endothelial cells, overexpression of TRPV4 seems to have an opposite effect on RhoA activity." (PMID 34356643, 2021). "In tumor endothelial cells (TECs), TRPV4-mediated Ca2+-influx impacts actin dynamics and migration of TECs in a membrane-stretch-dependent manner." (PMID 34356643, 2021). "In contrast, stimulation of TRPV4 in the same model system leads to normalization of the vascular endothelium through restored mechanosensitivity and inhibits tumor growth." (PMID 34356643, 2021). "For tumor tissue data mined from TCGA, TRPV4 expression was highest in kidney renal clear cell carcinoma (KIRC) and lowest in LAML." (PMID 34262942, 2021). "In the current study, we demonstrate that tumor derived-EVs downregulate endothelial TRPV4 channels post-translationally and induce abnormal angiogenesis via Rho/Rho kinase/YAP/VEGFR2 pathway." (PMID 35004649, 2021). "For instance, in tumor endothelial cells, the deletion of the TRPV4 gene induces cell proliferation, migration, sprouting angiogenesis, and abnormal tube formation in vitro accompanied by an increase in basal Rho activity." (PMID 33981725, 2021). "To determine the clinical relevance between TRPV4 and tumor metastasis in CRC, we investigated 106 CRC specimens with or without local metastasis to lymph-nodes." (PMID 34814869, 2021). "The results revealed that copy number values were positively correlated with TRPV4 expression, while methylation levels were negatively correlated with TRPV4 expression in most tumor types from TCGA." (PMID 34262942, 2021). "We first assessed TRPV4 expression in tumor tissue samples from TCGA and normal tissue samples from TCGA and the GTEx database." (PMID 34262942, 2021). "High expression of TRPM4 and TRPM7 was detected in primary tumor biopsies, while TRPV4, TRPC4, TRPC6 and especially TRPV6 expression was limited, while the expression of TRPC1 and TRPV2 are moderately expressed." (PMID 34936030, 2021).
tumor (continued). "These contrasting results highlight the challenge with targeting these channels in a heterogeneous tumour, and suggest that TRPV4 can have both pro- and antitumorigenic properties." (PMID 32825277, 2020). "Subcutaneous injection of Lewis Lung Carcinoma cells in TRPV4 knockout mice leads to increased vascular density, higher vessel diameter, and reduced pericyte coverage, overall resulting in enhanced tumor growth." (PMID 33132914, 2020). "One study reported that pharmacological activation of TRPV4 by GSK1016790A drastically enhances tumor cells death mainly via two routes: apoptosis mediated by PARP-1 cleavage and oncosis accompanied with a rapid decrease of intracellular ATP production." (PMID 32211326, 2020). "Activation and/or overexpression of TRPV4 induces normalization of the tumor vasculature and decreases tumor endothelial cell migration." (PMID 32887220, 2020). "We found that repression of TRPV4 significantly slowed the subcutaneous tumor invasion-growth compared to the control group." (PMID 32843668, 2020). "When TRPV4 is continuously activated, the expressions of genes that facilitate tumor metastasis increase, but those of genes that inhibit metastasis reduce." (PMID 31235786, 2019). "Beyond that, the expression level of transient receptor potential ion channel, subfamily V, member 4 (TRPV4) vary in different tumors and play important role in multiple processes of tumor progression." (PMID 31235786, 2019). "At the initial stage of inflammation, cathepsin produced by the microenvironment of tumor inflammation can simultaneously activate TRPV4 and proteinase 2 which then synergize to continue the development of inflammatory response." (PMID 31235786, 2019). "As summarized above, TRPV4 is closely related with proliferation, differentiation, apoptosis, and migration of tumor cell by regulation of Ca2+ and its downstream, then finally participates in tumor onset and progression." (PMID 31235786, 2019). "TRPV4 regulates cellular function by modulating calcium signaling, and finally participates in tumor onset and progression." (PMID 31235786, 2019). "We found that treatment with TRPV4 shRNA resulted in a significant reduction in tumor volume and weight compared with the shScramble group." (PMID 31189890, 2019). "However, the findings from our study, for the first time, show that tumor-derived EVs target a mechanosensitive calcium channel, TRPV4 and transforms normal EC to tumor EC-like phenotype, which may explain the mechanisms underlying the abnormal vasculature in the tumor." (PMID 31921855, 2019). "Taken together, our results suggest that the pathological (tumor) microenvironment transforms normal endothelial cells into a tumor endothelial cell-like phenotype through EVs via the downregulation of TRPV4." (PMID 31921855, 2019). "In short, inhibition of tumor angiogenesis by targeting TRPV4 should be based on a thorough understanding of the organ specificity of the tumor microenvironment." (PMID 31235786, 2019). "It is well-documented that the expression level of TRPV4 in tumor cells was positively correlated with their metastatic ability." (PMID 31235786, 2019). "When inflammatory response occurs, inflammatory factors recruit immune cells, and activation of the TRPV4 channel therein enables tumor cells to escape from the immune system." (PMID 31235786, 2019). "With the study mentioned before, these results demonstrate the tumor angiogenesis regulatory role of TRPV4." (PMID 31235786, 2019). "In TRPV4 knockout mice, the density and diameter of new tumor blood vessels enlarge, and the coverage of surrounding tumor capillary endothelial cells shrinks." (PMID 31235786, 2019). "In summary, this review clarified the roles of TRPV4 in tumor onset, progression, and metastasis together with the mechanisms, verifying its potential antitumor effects." (PMID 31235786, 2019).
tumor (continued). "Collectively, TRPV4 probably affect cell proliferation, differentiation, apoptosis, and migration by regulating Ca2+ and production of isoforms, thus affecting tumor onset and progression." (PMID 31235786, 2019). "Being closely related to the prognosis of tumor patients, TRPV4 is probably one of the main participants in tumor metastasis." (PMID 31235786, 2019). "TRPV4 has been the first endothelial Ca2+-permeable channel to be clearly involved in tumor vascularization." (PMID 29324706, 2018). "To study the molecular mechanisms underlying the process of tumor infiltration of the peripheral nerves, we quantified two key transducers, TRPV1 and TRPV4, within the neuronal cells by immunofluorescence and Western blotting." (PMID 29637027, 2018). "TRPV4 channels are also important players in tumor vascularization by regulating endothelial cell migration (see chapter “TRP channels in tumor vascularization”)." (PMID 29772843, 2018). "In our study, we concurrently studied the expression of ERK1/2 with TRPV4 to get an indication for tumor progression." (PMID 29637027, 2018). "TRPV4 activation and overexpression likely normalized the abnormal angiogenesis evoked by tumor ECs through the inhibition of the exacerbated Rho activity." (PMID 30559679, 2018). "After mapping AKT/E-cad signaling axis as a potential mode of action of TRPV4 in metastasis, secretomics was performed to attain a more comprehensive of how TRPV4 regulates metastasis by modulating the tumor microenvironment." (PMID 28530703, 2017). "The distribution plots show that, TRPV4 expression is significantly and positively correlated with grade and tumor size." (PMID 28530703, 2017). "Next, we inspect if TRPV4 expression correlates with key clinical-pathological parameters such as tumor grade and tumor size." (PMID 28530703, 2017). "Our latest findings revealed that decreased functional expression of TRPV4 plays a role in the aberrant mechanical properties of TEC (tumor endothelial cells), which we were able to rescue with overexpression or pharmacological activation of TRPV4." (PMID 27029071, 2016). "We further demonstrated that TRPV4 activation normalized the tumor vasculature in WT mice injected with tumors, to promote efficient chemotherapeutic drug delivery and reduce overall tumor growth." (PMID 27029071, 2016). "Our findings suggest that TRPV4 channels regulate tumor angiogenesis by selectively inhibiting tumor endothelial cell proliferation." (PMID 26388427, 2015). "Recently, we demonstrated, for the first time, mechanosensitive TRPV4 channels regulate tumor angiogenesis by modulating Rho-dependent EC mechanosensitivity." (PMID 26388427, 2015). "We found that treatment with GSK, together with anticancer drug Cisplatin, significantly inhibited tumor growth, suggesting that activation of TRPV4 normalizes tumor angiogenesis and improves delivery of chemotherapeutic drugs." (PMID 26388427, 2015). "TRPC1 and TRPV4 regulate endothelial cell calcium homeostasis, TRPM is associated with cell invasion, and TRPM4 plays an important role in lymph node spread of well-differentiated tumor cells." (PMID 41331166, 2025). "TRPV4 is a calcium (Ca2+) permeable non-selective cation channel 10 that controls angiogenesis by acting on the tumor endothelial cells, and is associated with matrix stiffness." (PMID 39895789, 2025). "Additionally, antagonists and agonists of the mechanosensitive receptor TRPV4 are also being used in trials for tumor intervention therapy." (PMID 41282026, 2025). "Furthermore, the expression of TRPV2, TRPV4 and TRPV6 was found to increase according to the tumor stage with an association with poor prognosis, particularly in advanced stages." (PMID 39125864, 2024).